MGMT (O-6-methylguanine-DNA methyltransferase)
Diseases named in the same sentence as MGMT in open-access papers (continued):
Sharing a sentence is not in itself a finding about the gene and the disease.
thymoma (5 papers, 2016 to 2024). A neoplasm arising from the epithelial cells of the thymus. "Interestingly, promoter methylation of the CDKN2A gene was reported in up to 11% of thymomas and 25% of thymic carcinoma, while aberrant MGMT methylation and loss of its protein expression was more frequent in thymic carcinoma than in thymoma." (PMID 27999265, 2016). "Similarly, MGMT methylation is more prevalent in TCs (74%) than in thymomas (29%), especially in advanced stages, and CDKN2 promoter methylation occurs in up to 25% of TCs and in 14% of thymomas." (PMID 38338833, 2024). "To further address this issue, we investigated MLH1, MGMT, CDKN2A, and RASSF1A methylation levels in blood samples and surgically resected thymomas from 69 patients with TAMG and in the adjacent normal thymus available from 44 of them." (PMID 33192293, 2020). "The methylation levels of the DNA repair and tumor suppressor genes MLH1, MGMT, CDKN2A, and RASSF1A have frequently been investigated in thymic epithelial tumors (TETs), including thymomas." (PMID 33192293, 2020). "In summary, the present study reveals that the promoter methylation levels of MLH1, MGMT, CDKN2A, and RASSF1A genes are not increased in thymomas with respect to the healthy tissues of patients with MG and do not correlate with histological or pathological features." (PMID 33192293, 2020).
acute myeloid leukemia (4 papers, 2016 to 2025). Acute myeloid leukemia (AML) is a group of neoplasms arising from precursor cells committed to the myeloid cell-line differentiation. "In human acute myeloid leukaemia (AML) patients, for example, TMZ demonstrated modest clinical activity, but only when patients were pre‐screened for low MGMT expression." (PMID 40377133, 2025). "In addition, temozolomide has shown significant therapeutic promise in recent clinical studies of acute myeloid leukemia (AML), a finding that also requires knowledge of MGMT activity." (PMID 27035132, 2016).
laryngeal carcinoma (4 papers, 2015 to 2024). Carcinoma that arises from the laryngeal epithelium. "Research has indicated that methylation of the MGMT promoter is linked to enhanced response to temozolomide in patients suffering from glioblastoma, and comparable studies concerning laryngeal cancer are currently in progress." (PMID 39452555, 2024). "In the present report, the MGMT gene was identified to exhibit a frequent methylation rate in LSCC, which may indicate that the occurrence of laryngeal cancer is associated with promoter methylation of the MGMT gene." (PMID 25452816, 2015). "The hypermethylation of the O6-methylguanine-DNA methyltransferase (MGMT) promoter is one of the most clinically significant instances of DNA methylation in laryngeal cancer." (PMID 39452555, 2024). "The data provides a foundation for further investigations into the role of the MGMT gene in laryngeal carcinoma and its potential as a biomarker in the early diagnosis, treatment and prognosis of laryngeal carcinoma." (PMID 25452816, 2015). "Treatment of laryngeal carcinoma HEp-2 cells with Aza appeared to reverse the MGMT gene methylation status and demethylate the promoter region." (PMID 25452816, 2015). "In the present study, it was identified that DNA hypermethylation-silenced MGMT in laryngeal carcinoma HEp-2 cells is characterized by H3K9 hypermethylation, and H3K9 and H3K4 hypomethylation at the promoter." (PMID 25452816, 2015). "The DNA methylation rate of MGMT was significantly higher in laryngeal cancer (54%) compared with 24% in the healthy control group (P<0.05; data not shown)." (PMID 25452816, 2015). "Notably, the less frequently methylated genes (less than 30%) were as follows: CDH13, p16, MGMT, GAL, NPY, GALR2, and VEGFR3 for hypopharyngeal cancers; CDH13, p16, RASSF1A, GAL, NPY, and NPY1R for laryngeal cancers; and CDH13 and GAL for oral cavity cancers." (PMID 29361757, 2018).
lung adenocarcinoma (4 papers, 2011 to 2023). A carcinoma that arises from the lung and is characterized by the presence of malignant glandular epithelial cells. "In a study of 169 lung adenocarcinomas, rs1625649 was found to be modestly associated with MGMT methylation." (PMID 29036186, 2017). "MGMT (O6-Methylguanine DNA methyltransferase) is a DNA repair enzyme that is inactivated in 24–48% of lung adenocarcinomas." (PMID 24212941, 2011). "However, the authors were not able to reproduce the findings of Su and colleagues, as no changes in DNAm from miners exposed for 24 years to the α-emitter plutonium-239 at the Russian nuclear enterprise MAYAK were detected in the MGMT promoter of lung adenocarcinomas." (PMID 37891670, 2023). "To investigate if MMP-7 and MGMT are downstream genes of Ascl1, we overexpressed Ascl1 in human lung adenocarcinoma cells H441 which are normally negative for Ascl1 expression." (PMID 23300791, 2012).
metastatic disease (4 papers, 2011 to 2024). "Based on the results, the combinatorial presence of mutated Kras (codon 12) and methylated RASSF1A, FHIT and MGMT genes better characterize advanced tumor stage, metastatic disease, higher grade tumors and presence of lymphatic invasion than when considered separately." (PMID 23573237, 2013). "Of these five tumor pairs, four pairs demonstrated MGMT methylation at both sites (primary and liver metastatic tumors) with an increase in methylation density." (PMID 22132162, 2011). "When paired primary and metastatic tumors were compared, only MGMT methylation was significantly higher in metastatic cancers (27.4% vs. 13.4%, P = .013), and this difference was due to an increase in methylation density rather than frequency in the majority of cases." (PMID 22132162, 2011). "Overall, advanced tumor stage (97%), metastatic disease (100%), moderately to poorly differentiated tumors (84%) and presence of lymphatic invasion (92%) were more frequently observed in tumors with mutated Kras (codon 12) and methylated RASSF1A, FHIT and MGMT genes." (PMID 23573237, 2013). "Mean MGMT methylation levels were not significantly different in patients with metastatic disease (p=0.19) vs those with single vs multiple tumours (p=0.31), or those with a second synchronous primary tumour (p=0.32)." (PMID 36198483, 2023). "Similarly, the INT validation cohort is relatively small sized and retrospective in nature, including both patients who did and did not develop metastatic disease, and MGMT status was here assessed with a different method." (PMID 39618336, 2024).
nasopharyngeal carcinoma (4 papers, 2014 to 2021). A carcinoma arising from the nasopharyngeal epithelium. "Our previous work showed that MGMT-proficient nasopharyngeal carcinoma cells are more resistant to CDDP cytotoxicity than MGMT-deficient cells." (PMID 31450627, 2019). "UBE2B regulates the sensitivity of nasopharyngeal carcinoma (NPC) cells to carmustine (BCNU) by ubiquitination of MGMT (a DNA repair enzyme)." (PMID 33810518, 2021). "Here, we explored the interactions between MGMT and the HR pathway in CDDP-activated DDR and their clinical implications in nasopharyngeal carcinoma (NPC)." (PMID 33397362, 2021). "After analyzing clinical outcomes of 83 patients with nasopharyngeal carcinoma receiving CDDP-based therapies, we also observed that high expression levels of MGMT in tumor specimens predict worse survival outcomes." (PMID 31450627, 2019).
pilocytic astrocytoma (4 papers, 2012 to 2023). Pilocytic astrocytoma is a rare subtype of low-grade glioma of the central nervous system characterized by a well circumscribed, often cystic, brain tumor with a discrete mural nodule and long, hair-like projections that extend from the neoplastic astrocytes. "The most common histological diagnosis was metastasis in five patients; one patient had a pilocytic astrocytoma (Grade 1 WHO) and one GBM (IDH wild type, ATRX preserved, MGMT 9%, Grade 4 (WHO))." (PMID 37623528, 2023).
sarcoma (4 papers, 2012 to 2023). A usually aggressive malignant neoplasm of the soft tissue or bone. "Response to temozolomide has been noted in a patient with a resistant undifferentiated high grade sarcoma whose tumor demonstrated MGMT promoter methylation and protein loss by IHC." (PMID 25906748, 2015). "In fact, it has been reported that another gene, ROCK2, often overexpressed in some types of sarcomas, may act as a DNA repair gene when MGMT is repressed, providing dacarbazine resistance to sarcomas." (PMID 37371106, 2023). "There was overexpression or loss of other sarcoma relevant proteins such as SPARC, PTEN and MGMT." (PMID 25906748, 2015). "There was low expression of MGMT in 65.3% of the sarcomas overall." (PMID 25906748, 2015). "Of note, MGMT promoter methylation occurred across all sarcoma subtypes, without preference for a specific entity." (PMID 23110891, 2012).
soft tissue sarcoma (4 papers, 2008 to 2023). A malignant neoplasm arising from muscle tissue, adipose tissue, blood vessels, fibrous tissue, or other supportive tissues excluding the bones. "Similar results were shown in a study of 62 soft tissue sarcomas with MGMT methylation 33.9% (21/62) and KRAS mutations 3.7% (2/62)." (PMID 27643594, 2016). "The purpose of this study was to assess the frequency of MGMT promoter methylation in soft tissue sarcoma to identify patients eligible for alkylating agent chemotherapy such as temozolomide." (PMID 23110891, 2012). "MGMT gene silencing is a rare event in soft tissue sarcoma and cannot be recommended as a selection criterion for the therapy of STS patients with alkylating agents such as temozolomide." (PMID 23110891, 2012). "Despite differences in methods, patient populations and tumor subtypes in the present and the previously published studies, it is obvious that MGMT gene silencing is a rare event in soft tissue sarcoma." (PMID 23110891, 2012). "Epigenetic silencingof MGMT and/or other key regulatory genes in tumor cells may play a role intemozolomide resistance, and in the pathogenesis of soft tissue sarcomas." (PMID 19043564, 2008). "The purpose of the present study was to determine the frequency of MGMT gene silencing in soft tissue sarcoma in order to identify patients and/or histological subtypes that may be suitable for treatment with alkylating agents and irradiation in the setting of a phase II trial." (PMID 23110891, 2012). "In this retrospective study, the methylation status of the MGMT promoter in histological tumor samples from patients with LMS, dacarbazine-based regimens-treated, was measured and correlated with clinical outcomes aimed at optimizing the use of dacarbazine in soft tissue sarcomas." (PMID 37371106, 2023).
thalassemia (4 papers, 2019 to 2025). An inherited blood disorder characterized by a decreased synthesis of one of the polypeptide chains that form hemoglobin. "Examples include hypermethylation of O6-methylguanine-DNA-methyltransferase (MGMT), 1p19q co-deletion, isocitrate dehydrogenase (IDH) gene mutations 1 and 2, and inactivating mutations of alpha-thalassemia/mental retardation syndrome X-linked (ATRX)." (PMID 32005184, 2020). "However, the mean difference did not reflect the genetic status of 1p/19q, α-thalassemia/mental retardation syndrome-X-linked (ATRX) gene, or O6-methylguanine-DNA-methyltransferase (MGMT)." (PMID 40352771, 2025).
alpha thalassemia-X-linked intellectual disability syndrome (3 papers, 2020 to 2025). X-linked alpha thalassaemia mental retardation (ATR-X) syndrome in males is associated with profound developmental delay, facial dysmorphism, genital abnormalities and alpha thalassaemia. "Both alpha-thalassemia x-linked intellectual disability syndrome (ATRX) gene mutation and MGMT promoter methylation occurred less frequently in cluster 3 than in other clusters." (PMID 36267281, 2022).
Aphasia (3 papers, 2020 to 2024). An acquired language impairment of some or all of the abilities to produce or comprehend speech and to read or write. "A 41-year-old male, with transient motor aphasia at initial diagnosis, was diagnosed with a left parietal GBM (IDH-mutated, MGMT-methylated) in 2020, according to the 2016 WHO classification update." (PMID 37665396, 2023). "Age, KPS, MGMT status, the extent of resection, aphasia after surgery and motor dysfunction after surgery were significantly associated with OS on univariate analysis (p < 0.05)." (PMID 32375830, 2020). "Notably, prognostic factors for PFS included sex, caregiver, tumor location, JCS, aphasia before adjuvant TMZ, MGMT promoter methylation status, and IDH gene mutation status." (PMID 39659832, 2024). "On UVA, the age upon diagnosis (p < 0.001), the MGMT promotor methylation status (p 0.035), the KPS (p < 0.001), the EOR (p 0.004), the presence of motor deficits after surgery (p 0.001) as well as the presence of aphasia after surgery (p 0.044) were significantly associated with the OS." (PMID 32375830, 2020).
brain glioma (3 papers, 2020 to 2025). A malignant glioma that involves the brain. "Several mutated genes specific to brain glioma have been found in exosomes, such as MGMT, PTEN, EGFR, and many others." (PMID 35448031, 2022).
Central Nervous System Lymphoma (3 papers, 2020 to 2025). "Similarly, patients with primary central nervous system lymphoma (PCNSL) responded to TMZ better when their tumour cells harboured low MGMT levels." (PMID 40377133, 2025).
cervical disease (3 papers, 2018 to 2023). "Thus, the detection of the promoter methylation of MGMT gene could help clinicians to find out the progression of cervical carcinogenesis and even whether the patients with cervical disease is recovering or getting worse, which would improve the accuracy of diagnostic for cervical cancer." (PMID 31574102, 2019). "The promoter methylation statuses of DAPK1, MGMT, and RARB were positively correlated with the cervical disease grades, respectively." (PMID 29850477, 2018). "The methylation rates of IFN-γ, FHIT, MGMT, CDKN2A, SALL3, and gene promoters were significantly higher in cervical cancer tissues than those in CIN and normal cervical tissues, which are related to the progression of cervical oncogenesis." (PMID 29850477, 2018). "HPV status may change over time and a PAP smear may produce false-negative results, so in such cases MGMT methylation analysis may help identify the patients’ cervical disease status (NIL, precancer or cancer)." (PMID 37834832, 2023).
colorectal adenocarcinoma (3 papers, 2014 to 2023). The most common type of colorectal carcinoma. "ERCC1 was methylated in 44.6% of colorectal adenocarcinoma while MGMT was methylated in 69% of cases." (PMID 37510370, 2023). "MGMT staining was always nuclear in colorectal adenocarcinoma gland cells and always detected in surrounding tissue." (PMID 25015560, 2014). "Therefore, a significant difference in ERCC1 and MGMT methylation between normal tissues and colorectal adenocarcinoma was reached (p ≤ 0.001)." (PMID 37510370, 2023). "Another study of four candidate genes in colorectal adenocarcinoma cells demonstrated that males had increased methylation of MTHFR, CALCA, and MGMT compared to females." (PMID 27795744, 2016). "MGMT and CD133 expression was analyzed by immunohistochemistry in 123 paraffin-embedded colorectal adenocarcinoma samples, obtaining the percentage staining and intensity." (PMID 25015560, 2014).
ductal adenocarcinoma (3 papers, 2010 to 2024). "The positive rates of MGMT, ERCC1, hMSH2, and hMLH1 were significantly lower in ductal adenocarcinoma than those in non-cancerous tissues of group B (P <0.05)." (PMID 24502441, 2014). "No statistical differences were found among the positive rates of MGMT, ERCC1, hMSH2, and hMLH1 in ductal adenocarcinoma and non-cancerous pancreatic tissues of group A (P >0.05)." (PMID 24502441, 2014). "Expression of MGMT, ERCC1, hMSH2, and hMLH1 had no obvious correlation with the size of tumor mass and differentiation degree of ductal adenocarcinoma (P >0.05)." (PMID 24502441, 2014). "The positive rates of MGMT, ERCC1, hMSH2, and hMLH1 were significantly lower in ductal adenocarcinoma than those in non-cancerous pancreatic tissues in group A + group B (P <0.01 or P <0.05)." (PMID 24502441, 2014).
gastritis (3 papers, 2019 to 2023). Inflammation of the stomach. "Remarkably, H. pylori cagA-positive-induced gastritis is associated with CpG hypermethylation of MGMT, the gene encoding the DNA repair protein O6-methylguanine DNA methyltransferase (MGMT)." (PMID 37763093, 2023).
goiter (3 papers, 2019 to 2023). Enlargement of the thyroid gland usually caused by lack of iodine in the diet, hyperthyroidism, or thyroid nodules. "Our data showed that the promoter methylation of SLC5A8, Ras association domain family member 1(RASSF1), and MGMT were significantly different between PTC tissue and goiter with P-value less than 0.05." (PMID 31754358, 2019). "In Khatami’s study, in PTC patients, the methylation of two O6-methylguanine-DNA methyltransferase (MGMT) promoter areas (c) and (d) was considerably higher than in goiter controls, suggesting that MGMT may be associated with PTC." (PMID 37762070, 2023). "In this research, we determined the promoter methylation status of four tumor suppressor genes (SLC5A8, RASSF1, MGMT, and DNMT1) and compared the results of 55 PTC cases with 40 goiter patients." (PMID 31754358, 2019). "However, our results indicated that DNMT1 methylation in PTC patients, in comparison with goiter patients (controls), was less than SLC5A8, RASSF1, and MGMT." (PMID 31754358, 2019).
Hypertension (3 papers, 2023 to 2026). The presence of chronic increased pressure in the systemic arterial system. "Additionally, a history of hypertension was associated with MGMT promoter methylation after multivariate adjustment (adjusted OR, 3.6; p = 0.03)." (PMID 41682986, 2026). "The reported factors associated with early readmission in GBM patients were reduced overall physical performance determined via KPS, discharge disposition other than home, MGMT methylation status, location of tumor in eloquent brain areas, or intra-operative hypertension." (PMID 37568723, 2023).
leiomyosarcoma (3 papers, 2012 to 2023). An uncommon, aggressive malignant smooth muscle neoplasm, usually occurring in post-menopausal women. "Of note, our research group is currently conducting an observational study to investigate whether MGMT expression levels or MGMT promoter methylation may represent a predictive marker for dacarbazine sensitivity in leiomyosarcoma and solitary fibrous tumours." (PMID 33902630, 2021).
liver cancer (3 papers, 2022 to 2025). An epithelial or non-epithelial malignant neoplasm that arises from the liver. "To elucidate mechanisms of NDMA-induced liver cancer progression, we performed longitudinal analyses of phenomic, transcriptomic, and phosphoproteomic changes in wild-type and MGMT-deficient mice, observing amplified responses in the deficient genotype." (PMID 41256671, 2025).
ovarian tumors (3 papers, 2013 to 2024). "In an independent set of 378 ovarian tumours from the AGO-OVAR 11 study, variants near MGMT and PPP2R5C correlated with methylation and transcript levels, and PPP2R5C mRNA levels predicted progression-free survival in patients with residual disease." (PMID 38443389, 2024). "Aberrant methylation of GSTP1 and MGMT were exclusively demonstrated in invasive ovarian carcinomas, differentiating between ovarian tumors with low malignant potential and invasive ovarian tumors." (PMID 24086249, 2013).